TRAPPC9 (trafficking protein particle complex subunit 9)
Description:
Functions as an activator of NF-kappa-B through increased phosphorylation of the IKK complex. May function in neuronal cells differentiation. May play a role in vesicular transport from endoplasmic reticulum to Golgi.
Synonyms: KIAA1882; NIBP; T1; IKBKBBP; TRS120; MRT13; IBP
Tractability: PROTAC: ubiquitination databases record sites on it; its protein half-life has been measured.
Gene: Protein-coding gene on chromosome 8 (139,727,725 to 140,458,579, reverse strand). Ensembl gene ENSG00000167632.
Subcellular location: Golgi apparatus, cis-Golgi network; Endoplasmic reticulum; Cytoplasm
Subcellular location (Human Protein Atlas): Golgi apparatus; Vesicles; Nucleoplasm
Pathways (Reactome):
Vesicle-mediated transport: COPII-mediated vesicle transport; RAB GEFs exchange GTP for GDP on RABs
Gene Ontology:
Molecular function: protein binding
Biological process: cerebral cortex development; endoplasmic reticulum to Golgi vesicle-mediated transport; vesicle coating
Cellular component: TRAPP complex; cytoplasm; cytosol; TRAPPII protein complex; endoplasmic reticulum; Golgi apparatus
Genetic constraint (gnomAD): Loss-of-function variants: 78 observed, 119.85 expected, observed/expected ratio (o/e) 0.65, 90% interval 0.54 to 0.79. The upper end of that interval is the gene's LOEUF score, 0.79, which puts it in group 3 of 6, group 1 being the genes least tolerant of losing a copy. Missense variants: 1,296 observed, 1,534.5 expected, observed/expected ratio (o/e) 0.84, 90% interval 0.81 to 0.88. Synonymous variants: 638 observed, 628.27 expected, observed/expected ratio (o/e) 1.02, 90% interval 0.95 to 1.08.
Gene-disease validity (ClinGen):
ClinGen rates the evidence that TRAPPC9 causes each of these diseases.
intellectual disability-obesity-brain malformations-facial dysmorphism syndrome (autosomal recessive): Definitive.
Homologues: Orthologues: chimpanzee TRAPPC9 (99% identical), dog TRAPPC9 (95% identical), guinea pig TRAPPC9 (92% identical), rat Trappc9 (92% identical), mouse Trappc9 (92% identical), pig TRAPPC9 (92% identical), rabbit TRAPPC9 (88% identical), tropical clawed frog trappc9 (79% identical), macaque TRAPPC9 (76% identical), zebrafish TRAPPC9 (68% identical), Drosophila melanogaster brun (36% identical), Caenorhabditis elegans trpp-9 (24% identical), and 1 more.
Diseases named in the same sentence as TRAPPC9 in open-access papers:
TRAPPC9 is named in the same sentence as 62 diseases in open-access papers, as found by Europe PMC text mining. Sharing a sentence is not in itself a finding about the gene and the disease. The quoted sentences say what the papers report.
Intellectual disability (23 papers, 2011 to 2024). "The TRAPPC9 gene associated with various diseases, including intellectual developmental disorder, autosomal recessive disorder 13, and intellectual disability-obesity-brain malformations-facial dysmorphism syndrome." (PMID 39045327, 2024). "Mutations in the TRAPPC9 gene are associated with autosomal recessive intellectual disability and mental retardation." (PMID 39365306, 2024). "Loss-of-function TRAPPC9 mutations manifest microcephaly, intellectual disability, and obesity in patients." (PMID 37416774, 2023). "The clinical spectrum related to TRAPPC9 mutations also include non-syndromic intellectual disability autism and severe developmental delay." (PMID 36348459, 2022). "In this study, we reported a novel homozygous mutation in TRAPPC9 gene causing autosomal recessive intellectual disability in a consanguineous family from Sudan." (PMID 36348459, 2022). "More recently, missense mutations in TRAPPC9 gene have been reported in three patients with intellectual disability and biochemical abnormalities consistent with Congenital disorder of glycosylation." (PMID 36348459, 2022). "A nine-year-old wheelchair-bound female with cerebral palsy and intellectual disability secondary to trafficking protein particle complex subunit 9 (TRAPPC9) mutation presented to the family medicine clinic after not having passed stool for six days." (PMID 36475161, 2022). "In this study, we reported a novel homozygous mutation in TRAPPC9 gene causing autosomal recessive intellectual disability in a Sudanese family." (PMID 36348459, 2022). "Patients with TRAPPC9 mutations in previous studies displayed intellectual disability, developmental delay, microcephaly, and brain abnormalities." (PMID 33513295, 2021). "Similar to patients with TRAPPC9-deficiency associated intellectual disability, homozygous Trappc9 deficient mice show a reduction in brain size (microcephaly), increase in body weight and fat mass (obesity) and behavioral abnormalities." (PMID 32877400, 2020). "Microcephaly and intellectual disability are amongst the most common features of patients with TRAPPC9 mutations and similar decreases in brain size and behavioral changes are observed in homozygous Trappc9 deficient mice." (PMID 32877400, 2020). "One rare form of intellectual disability is secondary to the loss of TRAPPC9, an activator of NF‐κB and a mediator of intracellular protein processing and trafficking." (PMID 32162493, 2020). "The patients’ phenotype was consistent with a TRAPPC9 defect, which is characterized by severe intellectual deficiency (ID), postnatal microcephaly, abnormalities of the corpus callosum, cerebellum, and white matter, as found in our patients." (PMID 29693325, 2018). "Mutations in the maternal allele of Trappc9 result in mental retardation; therefore, we find it of particular interest that Trappc9 expression can be switched to paternal allele." (PMID 24927774, 2014). "The observation of partial imprinting for TRAPPC9 is notable and should be studied in brain since this gene has recently been shown to be mutated in autosomal recessive mental retardation." (PMID 21418647, 2011). "Genetic studies have linked alterations in TRAPPC9 to changes in brain structure and cognitive function, highlighting its significance in the study of neurodevelopmental biology and genetic disorders that result in intellectual disability." (PMID 39184350, 2024). "Notably, a GDD/ID child carried two novel mutations in the TRAPPC9 gene with the clinical manifestations of severe intellectual disability and autism." (PMID 39817275, 2022). "Besides microcephaly and intellectual disability, obesity is a phenotype commonly observed in TRAPPC9 loss-of-function patients." (PMID 32877400, 2020). "Hence, our study suggests a role for Trappc9 imprinting in brain development and brain control of energy balance, and provides a new mouse model for TRAPPC9-associated intellectual disability." (PMID 32877400, 2020).
Intellectual disability (continued). "For example, only recently TrappC9 (Trs120) was connected to cancer and schizophrenia in humans and inflammatory disease in cows, thus broadening its disease connection from the previously known association with intellectual disability." (PMID 27066478, 2016). "However, the mechanisms of how TRAPPC9 deficiency causes the neural phenotypes including microcephaly and intellectual disabilities in patients remains unknown." (PMID 37416774, 2023). "We demonstrate for the first time that disruption of the TRAPPII complex by Trappc9 deficiency results in defects of both axon and dendrite elongation and branching, which may be responsible for the microcephaly and intellectual disability seen in human patients." (PMID 37416774, 2023). "Trappc9 encodes a subunit of the intracellular trafficking protein particle II complex (TrappII), mutations of which lead to a neurodevelopmental disorder in humans and mice, which includes symptoms of postnatal microcephaly, intellectual disability and speech impairment." (PMID 36313557, 2022). "One such disorder is NIBP syndrome, characterized by microcephaly and intellectual disability, and caused by mutations of NIBP/TRAPPC9, a crucial and unique member of TRAPPII." (PMID 37416774, 2023). "In conclusion, the study adds to the phenotypic and genetic spectrum of MBOAT7- and TRAPPC9-related intellectual disability." (PMID 36672789, 2022). "TRAPPC9-related intellectual disability is an autosomal recessive disease with particular overrepresentation in consanguineous communities." (PMID 36348459, 2022). "Examples of newly added disease connections for TRAPP subunits include miscarriage for TrappC2, cancer for TrappC4, and TrappC9, intellectual disability and schizophrenia for TrappC9, and Alzheimer's disease for TrappC6." (PMID 27066478, 2016). "Mutations in TRAPP subunits TRAPPC9 and TRAPPC2 have been identified in patients with mental retardation and X-linked spondyloepiphyseal dysplasia tarda (SEDT), respectively." (PMID 21858081, 2011). "The TRAPPC9 gene has been reported to cause autosomal recessive forms of intellectual disabilities in 56 patients from consanguineous and non-consanguineous families around the world." (PMID 36348459, 2022). "TRAPPC9 knock-out mice exhibit a rare intellectual disability accompanied by an increase in fat mass and body weight, suggesting that expression of this gene may protect against obesity." (PMID 34937574, 2021). "A man previously diagnosed with autism spectrum disorder secondary to intellectual disability, absent speech and repetitive behaviors was found to have homozygous pathogenic variants in TRAPPC9." (PMID 32162493, 2020). "TRAPPC9 deficiency results in severe intellectual disability usually accompanied by absent or delayed speech, and microcephaly, with varied reports of stereotypic movements and dysmorphic features." (PMID 32162493, 2020). "NIBP/TRAPPC9 mutations are associated with non-syndromic autosomal recessive intellectual disability (NS-ARID), which is known as NIBP syndrome, and assigned as the intellectual disability-obesity-brain malformations facial dysmorphism syndrome in the human disease database Mala Cards." (PMID 39817275, 2022). "Mutations have previously been reported in several members of the TRAPP complex of proteins, including TRAPPC2, TRAPPC9 and TRAPPC11, resulting in disorders involving skeletal abnormalities, intellectual disability, speech impairment and developmental delay." (PMID 29391579, 2018). "In a similar experiment, we have further identified that the carboxyl terminus of TRAPPC9 is required for its interaction with TRAPPC2 and TRAPPC10, as deletional mutants of this domain found in some patients with intellectual disability failed to interact with TRAPPC2 or TRAPPC10." (PMID 21858081, 2011).
microcephaly (15 papers, 2011 to 2025). A congenital or acquired developmental disorder in which the circumference of the head is smaller than normal for the person's age and sex. "We focus on embryonic, postnatal, and adult neurogenic mechanisms responsible for microcephaly and white matter reduction after Trappc9 loss of function." (PMID 37416774, 2023). "Various types of homozygous null mutations of TRAPPC9 that lead to ARID along with microcephaly and occasionally seizure have been reported." (PMID 36672789, 2022). "TRAPPC9 LoF is associated with a rare recessive neurodevelopmental syndrome with obesity and postnatal microcephaly as the most prominent signs, the latter likely due to the role of this protein in postmitotic neurons." (PMID 36553552, 2022). "Trappc9-deficient mice have also been observed to have behavioral deficits such as global delay of intellectual development, postnatal microcephaly, thin corpus callosum with imbalance in dopamine D1 and D2 receptor containing neurons." (PMID 36672789, 2022). "Another study showed that microcephaly and obesity are common features of TRAPPC9-deficient patients (12/23 cases) and summarized this phenotype in a TRAPPC9-deficient mouse model." (PMID 35865874, 2022). "It was proposed that the MCPH1 defect acted as a modifier of a homozygous variant in TRAPPC9, a gene usually associated with postnatal microcephaly, which was heterozygous in the unaffected sister." (PMID 35456440, 2022). "Clinical manifestations of mutations associated with TRAPPC9 include ID, developmental delay, microcephaly, brain abnormalities, dysmorphic facial features, and obesity have been reported in previous studies." (PMID 33513295, 2021). "One of the most striking features of the patients with TRAPPC9 loss-of-function mutations is microcephaly." (PMID 32877400, 2020). "Loss-of-function mutations in human TRAPPC9 cause a rare neurodevelopmental syndrome characterized by microcephaly and obesity." (PMID 32877400, 2020). "In humans, both homozygous and compound heterozygous mutations in TRAPPC9 (NIBP) associate with developmental delay, microcephaly (95% reported cases), and obesity (52% reported cases)." (PMID 32877400, 2020). "Most previous reported cases with TRAPPC9 mutations presented with ID/developmental delay, microcephaly and brain abnormalities." (PMID 30853973, 2019). "The two siblings carrying compound heterozygous TRAPPC9 mutations presented with ID, developmental delay, microcephaly and brain abnormalities similarly to the clinical features found in almost cases with homozygous TRAPPC9 mutation in previous studies." (PMID 30853973, 2019). "The combination of these two TRAPPC9 mutations are most likely the cause of clinical features in the patients, especially ID, developmental delay, microcephaly and brain abnormalities." (PMID 30853973, 2019). "Of note, the clinical features including ID, developmental delay, microcephaly and brain abnormalities are observed in almost reported cases with TRAPPC9 mutations." (PMID 30853973, 2019). "We here report on two siblings with severe ID, microcephaly and hypoplasia of the corpus callosum, a homozygous TRAPPC9 mutation, and a homozygous MCPH1 truncation of BRCT3, and their normal sister with the homozygous MCPH1 mutation only." (PMID 29693325, 2018). "We report on two siblings with microcephaly and severe ID in whom exome sequencing revealed homozygous mutations in two genes, TRAPPC9 and MCPH1." (PMID 29693325, 2018). "Congenital, primary microcephaly in our patients suggests that TRAPPC9, like MCPH‐associated genes, plays a role in the production of the pool of neural progenitors that will allow for volumic development of the brain." (PMID 29693325, 2018). "Mutations in the TRAPP complex subunit 2 (TRAPPC2) cause X-linked spondyloepiphyseal dysplasia tarda, while mutations in the TRAPP complex subunit 9 (TRAPPC9) cause postnatal mental retardation with microcephaly." (PMID 21858081, 2011).
microcephaly (continued). "Similarly in mouse models, while the age of onset and progression of microcephaly is unclear, Trappc10-/- mice display more extensive brain size reduction and loss of white matter structures than Trappc9-/- mice." (PMID 35298461, 2022). "These cases include our proband and a report in which MCPH1 may act as a contributing cause of microcephaly through interaction with a biallelic TRAPPC9 variant." (PMID 35456440, 2022). "Loss of TRAPPC9 has been suggested to play a role in apoptotic signal in neurons leading to an increased cell loss during development, which resembles the clinical hallmark of microcephaly." (PMID 33513295, 2021). "Trappc9 deficient mice therefore exhibit microcephaly with parent-of-origin effects." (PMID 32877400, 2020). "Besides microcephaly, obesity is a common feature in TRAPPC9 deficient patients (12/23 patients) and this phenotype is recapitulated in the Trappc9 deficient mouse model." (PMID 32877400, 2020). "Mutations in TRAPPC9 alone have been associated with autosomal-recessive intellectual disability, developmental delay, autism, seizures, brain structure abnormalities, brain atrophy, and microcephaly in human subjects, with significant variability in the phenotypes of the disorders." (PMID 41300827, 2025). "In any case, a relevance of Trappc9 expression in NSCs is implied by the finding of reduced numbers of Sox2-positive stem cells in the subventricular zone and hippocampal subgranular zone of knock-out mice, which might be linked to their microcephaly phenotype." (PMID 36313557, 2022). "Moreover, studies of Trappc10-/- knockout mice revealed neuroanatomical brain defects and microcephaly, paralleling findings seen in the human condition as well as in a Trappc9-/- mouse model." (PMID 35298461, 2022). "Individuals with TRAPPC9-related disorder have postnatal-onset microcephaly." (PMID 35298461, 2022). "We retrieved from the DECIPHER database de novo <500 kb CNVs reported on patients with macrocephaly; in four cases, a candidate gene for macrocephaly could be pinpointed: a known microcephaly gene–TRAPPC9, and three genes based on their functional roles–RALGAPB, RBMS3, and ZDHHC14." (PMID 36553552, 2022). "Eight DECIPHER patients presented a CNV that encompassed a known microcephaly gene; one of these patients (DECIPHER 339955) carried a partial duplication of TRAPPC9." (PMID 36553552, 2022). "Identification of further affected families will help clarify the nature of the microcephaly in TRAPPC10-related disorder, as with TRAPPC9-related disorder where this was also unclear initially." (PMID 35298461, 2022). "We cannot rule out, however, that congenital microcephaly might have resulted from a combined effect of the TRAPPC9 and the MCPH1 mutations, either via a digenic interaction, or independently with the resulting phenotype being an overlap of features of both defects." (PMID 29693325, 2018).